CCDC158 (coiled-coil domain containing 158)
Description:
Plays a role in receptor-mediated endocytosis in proximal tubular cells of the kidney.
Synonyms: FLJ25770
Tractability: No criterion of Open Targets' tractability assessment is met for any kind of drug.
Gene: Protein-coding gene on chromosome 4 (76,312,997 to 76,421,868, reverse strand). Ensembl gene ENSG00000163749.
Subcellular location: Cytoplasmic vesicle, clathrin-coated vesicle; Early endosome
Gene Ontology:
Molecular function: clathrin binding; protein binding
Biological process: receptor-mediated endocytosis
Cellular component: clathrin-coated vesicle; early endosome
Genetic constraint (gnomAD): Loss-of-function variants: 64 observed, 82.37 expected, observed/expected ratio (o/e) 0.78, 90% interval 0.63 to 0.96. The upper end of that interval is the gene's LOEUF score, 0.96, which puts it in group 4 of 6, group 1 being the genes least tolerant of losing a copy. Missense variants: 915 observed, 1,003.6 expected, observed/expected ratio (o/e) 0.91, 90% interval 0.86 to 0.96. Synonymous variants: 330 observed, 357.24 expected, observed/expected ratio (o/e) 0.92, 90% interval 0.84 to 1.01.
Homologues: Orthologues: chimpanzee CCDC158 (99% identical), macaque CCDC158 (96% identical), rabbit CCDC158 (94% identical), rat Ccdc158 (92% identical), mouse Ccdc158 (92% identical), dog CCDC158 (91% identical), pig CCDC158 (91% identical), guinea pig CCDC158 (90% identical). Paralogues in human: MYH2 (20% identical), MYH8 (20% identical), MYH7 (20% identical), MYH1 (20% identical), MYH4 (20% identical), MYH6 (20% identical), MYH13 (19% identical), MYH3 (19% identical), MYH7B (19% identical), MYH11 (19% identical), MYH10 (18% identical), MYH9 (18% identical), and 32 more.
Diseases named in the same sentence as CCDC158 in open-access papers:
CCDC158 is named in the same sentence as 2 diseases in open-access papers, as found by Europe PMC text mining. Sharing a sentence is not in itself a finding about the gene and the disease. The quoted sentences say what the papers report.
nephrocalcinosis (1 paper, 2025). Nephrocalcinosis is a disorder that occurs when too much calcium is deposited in the kidneys. "The nearby CCDC158 is involved in renal proximal tubular endocytosis and is expressed in renal proximal tubular cells and in glomeruli of individuals free from nephrocalcinosis." (PMID 40554574, 2025).
CCDC158 also shares sentences with these, for which no sentence is quoted: tumor (1 paper).